LIMA1 (LIM domain and actin binding 1)
Diseases named in the same sentence as LIMA1 in open-access papers (continued):
Sharing a sentence is not in itself a finding about the gene and the disease.
head and neck cancer (1 paper, 2023). A primary or metastatic malignant neoplasm affecting the head and neck. "Only CALML5 showed significant prognostic value, while the prognostic value of CD59 and LIMA1 could not be validated in this cohort, emphasizing the necessity to assess the head and neck cancer specificity by subgroup analysis." (PMID 37274282, 2023).
Insulin resistance (1 paper, 2025). Increased resistance towards insulin, that is, diminished effectiveness of insulin in reducing blood glucose levels. "After HFD and CDAHFD diet feeding, the LIMA1 HKO/LIMA1ΔT662 mice exhibited systematic amelioration of MASLD‐related phenotypes, as indicated by the changes in insulin resistance (as shown by IPGTT and ITT), fast glycemia and TG contents, and serum ALT and AST levels." (PMID 39921472, 2025). "Additionally, compared with their AAV8‐TBG‐LIMA1‐WT counterparts, AAV8‐TBG‐LIMA1ΔT662 injection exhibited decreases in systemic insulin resistance, steatosis severity, inflammation and fibrosis in HFD‐fed and CDAHFD‐fed LIMA1 HKO (hepatocyte‐specific knockout) mice." (PMID 39921472, 2025).
invasive breast carcinoma (1 paper, 2026). A carcinoma that infiltrates the breast parenchyma. "Consistently, analysis of The Cancer Genome Atlas (TCGA) database showed that LIMA1 transcript levels were significantly lower in patients with invasive breast carcinoma than in healthy controls." (PMID 41596426, 2026).
liver cancer (1 paper, 2024). An epithelial or non-epithelial malignant neoplasm that arises from the liver. "For instance, CAF-derived exosomal miR-20a-5p promotes HCC progression through the LIMA1-mediated β-catenin pathway, while CAF-derived exosomal miR-1228-3p enhances the resistance of liver cancer cells to sorafenib (Zhang, Pan & Shao, 2023)." (PMID 39544420, 2024).
liver cirrhosis (1 paper, 2022). "In addition, we found that LIMA1 expression was moderately decreased in patients with liver cirrhosis induced by HBV infection but decreased in HCC patients, which suggests that LIMA1 expression might be associated with HCC progression." (PMID 36497115, 2022).
non-alcoholic fatty liver disease (1 paper, 2024). "Additionally, lipotoxic hepatocyte-derived LIMA1-enriched small EVs play a crucial role in promoting HSCs activation in non-alcoholic fatty liver disease (NAFLD)-related liver fibrosis by negatively regulating PINK1-mediated mitophagy." (PMID 39767572, 2024).
Obesity (1 paper, 2020). Accumulation of substantial excess body fat. "Based on the obtained results, the ZSCAN32, PLCD4, HOXC13, and ADCY9 from obesity predicted genes, as well as LIMA1, and SLC22A23 from CRC predicted genes were significantly related to CRC survival rate." (PMID 33073494, 2020).
osteosarcoma (1 paper, 2023). A usually aggressive malignant bone-forming mesenchymal neoplasm, predominantly affecting adolescents and young adults. "These suggest that LIMA1 may regulate osteosarcoma invasion by regulating cell adhesion and adherent patch changes." (PMID 37274282, 2023). "It is evident that SATB2-mediated invasion may be due to interference with LIMA1 expression, which is a key mediator of SATB2-regulated osteosarcoma invasion." (PMID 37274282, 2023).
periodontal disease (1 paper, 2024). "Among all SNPs for LIMA1, the most significant risk factor for periodontal disease was rs7315690, which exhibited the highest F statistic and the lowest p-value for correlation with LIMA1 (F = 1576.22, p = 4.92 × 10-3)." (PMID 39830509, 2024). "LIMA1 exhibited the strongest association with periodontal disease risk, underscoring its significance in the disease’s pathogenesis." (PMID 39830509, 2024). "MR analysis identified twenty-six significant genes, with LIMA1 (LIM domain and actin-binding 1) demonstrating a robust causal association with the progression of periodontal disease." (PMID 39830509, 2024). "Our results indicated that LIMA1 is associated with periodontal disease and shares genetic loci with specific mutations." (PMID 39830509, 2024). "This study highlights the role of mDCs and their markers, particularly LIMA1, in the pathogenesis of periodontal disease." (PMID 39830509, 2024). "Our findings demonstrate that mDCs markers play a pivotal role in the pathogenesis of periodontal disease, identifying several key markers, such as LIMA1, as potential targets for future preventive and therapeutic strategies." (PMID 39830509, 2024). "The identification of LIMA1 as a pivotal gene in periodontal disease progression opens new avenues for precision medicine approaches, potentially enhancing treatment efficacy and patient outcomes in periodontal management." (PMID 39830509, 2024). "The results demonstrated that LIMA1 functions as a downregulation switch gene in periodontal disease, with the expression profiles of their surface proteins and associated transcription factors undergoing significant changes over time, indicating their crucial role in monocyte development." (PMID 39830509, 2024).
periodontitis (1 paper, 2024). An acute or chronic inflammatory process that affects the tissues that surround and support the teeth. "MR analysis corroborated the inferences drawn from scRNA-seq, identifying ten causal gene markers associated with periodontitis, including LIMA1, PEA15, TMEM158, CMTM6, PDP1, FFAR4, VAC14, and ENHO." (PMID 39830509, 2024). "Through the integration of single-cell RNA sequencing and Mendelian randomization, we identified several key genetic markers that contribute to disease progression, with LIMA1 showing a strong association with periodontitis risk." (PMID 39830509, 2024). "The study found that LIMA1 demonstrated a strong correlation with the risk of periodontitis at the single-cell level, with expression levels significantly higher in patients with periodontitis compared to healthy individuals." (PMID 39830509, 2024). "In summary, the elevated expression of LIMA1 in patients with periodontitis suggests its potential as a diagnostic biomarker, which could aid in the early detection of the disease." (PMID 39830509, 2024). "Additionally, targeting the LIMA1 pathway may offer a promising therapeutic approach to modulate immune responses associated with periodontitis." (PMID 39830509, 2024). "In periodontitis patients, the odds ratio (OR) for LIMA1 was 1.17 (95% confidence interval (CI): 1.04–1.31), suggesting that LIMA1+ mDCs patients are 1.17 times more likely to develop periodontitis compared to LIMA1− mDCs patients." (PMID 39830509, 2024).
steatosis (1 paper, 2025). Increased lipid within the cytoplasm of cells. "Similarly, histopathological analysis of liver sections revealed alleviation of hepatic death and steatosis, and a reduction in inflammatory cell infiltration and fibrosis in the LIMA1 HKO/LIMA1ΔT662 mice compared to the LIMA1 HKO/LIMA1‐WT mice." (PMID 39921472, 2025). "The study revealed that steatosis upregulated HCF1 and OGT expression, leading to catalyzed O‐GlcNAcylation of LIMA1 protein and subsequent inhibition of its ubiquitin‐dependent degradation." (PMID 39921472, 2025). "Knockdown of LIMA1 led to decreased expression and nuclear localization of β‐catenin in cells with OPA‐induced steatosis." (PMID 39921472, 2025). "Mechanistic studies revealed that steatosis upregulated Host cell factor 1 (HCF1) and O‐GlcNAc transferase (OGT) expression, leading to catalyzed O‐GlcNAcylation at the T662 site of LIMA1 and subsequent inhibition of its ubiquitin‐dependent degradation." (PMID 39921472, 2025).
teratoma (1 paper, 2022). A non-seminomatous germ cell tumor characterized by the presence of various tissues which correspond to the different germinal layers (endoderm, mesoderm, and ectoderm). "Although Lima1 KO cells could give rise to teratomas, their size was substantially smaller compared to the tumours derived from WT ESC." (PMID 35105859, 2022). "However, the growth of the Lima1 KO teratomas, as well as the proportion of donor Lima1 KO cells in post-implantation embryos, were severely reduced." (PMID 35105859, 2022). "To understand whether Lima1 depletion affects the growth rate and/or the composition of solid tumours, we subcutaneously injected WT ESC or Lima1 KO ESC into SCID mice to generate teratomas." (PMID 35105859, 2022).
tumor (41 papers, 2008 to 2026). "Downregulation of LIMA1 is associated with tumor progression in breast, prostate, and oral cancers, whereas restoration of its expression inhibits cancer cell migration and invasion." (PMID 41596426, 2026). "And another study found that the expression of LIMA1 was upregulated in head and neck tumors, driving invasion and metastasis by activating tumor-associated pathways such as PI3K-AKT and JAK-STAT signaling pathways to promote the EMT process." (PMID 37274282, 2023). "One of the proteins identified was EPLIN (epithelial protein lost in neoplasia; encoded by the LIMA1 gene), a tumor suppressor known to inhibit cell migration and epithelial-to-mesenchymal transition." (PMID 33999101, 2021). "LIMA1 deficiency could lead to dysregulation of cytoskeletal dynamics, altered motility, and impaired intercellular adhesion, thereby promoting tumor proliferation, invasion, and migration." (PMID 39830509, 2024). "LIMA1 deficiency may be responsible for dysregulated cytoskeletal dynamics, altered cell motility and disrupted cell-cell adhesion, which can promote tumor proliferation, invasion, and migration." (PMID 37274282, 2023). "These associations show that LIMA1 plays a critical role in modulating HNSC tumor immunology." (PMID 37181789, 2022). "However, low levels of LIMA1 are associated with tumor growth, and LIMA1 binds to the known miR-142 target RAC1 while low levels of Cyclin B1 (CCNB1) are associated with reduced cell growth in accordance with a tumor-suppressive role of miR-142." (PMID 36291816, 2022). "Importantly, the deficiency of LIMA1 may be responsible for dysregulated cytoskeletal dynamics, altered cell motility and disrupted cell-cell adhesion, which promote tumor proliferation, invasion and migration." (PMID 37274282, 2023). "As Lima1 exhibited a broad expression in the foetus, loss of Lima1 may affect actin dynamics, membrane properties and adherens junctions in various tissues, which may also account for the reduced tumour growth and chimerism." (PMID 35105859, 2022). "Our findings position BPNT1 as a novel molecular scaffold that redirects STUB1’s catalytic activity toward LIMA1 degradation, resolving its tumor-promoting role in TNBC." (PMID 41540000, 2026). "Together, these findings suggest that LIMA1 in LRP5-overexpressing osteocyte-derived CM promotes an anti-tumor immune phenotype by driving M1 macrophage polarization in an LIMA1-dependent manner." (PMID 41596426, 2026). "Together, these results confirm that LIMA1 is a major contributor to the anti-tumor activity of CM derived from LRP5-overexpressing osteocytes." (PMID 41596426, 2026). "In contrast, our study uniquely targets tumor cells indirectly by modulating osteocytic LIMA1 secretion and its downstream interaction with MYO5B in cancer cells." (PMID 41596426, 2026). "Collectively, our findings define the LRP5/LIMA1/MYO5B axis as a novel signaling pathway that repurposes a canonical Wnt signaling component for tumor suppression." (PMID 41596426, 2026). "Together, these findings indicate that LIMA1 exerts its anti-tumor effects, at least in part, through interaction with MYO5B in EO771 cells." (PMID 41596426, 2026). "This study elucidates how the LRP5/Wnt signaling axis mediates anti-tumor effects by regulating the secretion of LIMA1 from osteocytes." (PMID 41596426, 2026). "This suggests that LIMA1 can enter tumor cells through a specific mechanism, where it binds to MYO5B and co-localizes with it." (PMID 41596426, 2026). "Knockdown of LIMA1 using shRNA reversed the anti-tumor effects of LRP5-overexpressing osteocyte-derived CM, confirming LIMA1’s role as a key downstream effector molecule of the LRP5/Wnt pathway." (PMID 41596426, 2026).
tumor (continued). "Collectively, these data demonstrate that BPNT1 scaffolds STUB1 recruitment to catalyze ubiquitin-dependent proteasomal degradation of LIMA1, thereby depleting this tumor suppressor in TNBC." (PMID 41540000, 2026). "LIMA1 silencing from a PDX derived from HNSCC#16 tumor with high LIMA1-alpha expression did not impact tumor size, while the number of invading cells in the zebrafish embryo xenograft model was statistically significantly decreased." (PMID 40676267, 2025). "Two years after the primary surgery, each patient ́s follow-up data in this HNSCC cohort was evaluated and combined with LIMA1 status analyzed by WB from the patient’s primary tumor." (PMID 40676267, 2025). "To further investigate the role of LIMA1 isoforms in HNSCC cancer, we collected a prospective HNSCC patient tumor tissue cohort, from which the expression of LIMA1 isoforms was studied by Western blotting with SC-136399 antibody (WB)." (PMID 40676267, 2025). "Treatment with miR-20a-5p-overexpressing CAFs exosomes inhibited LIMA1 expression and promoted aggressive tumor behavior in HCC." (PMID 38463229, 2024). "LIM domain and actin-binding protein 1 (LIMA1), as an important actin cytoskeletal regulator, was initially thought to be a tumor suppressor frequently downregulated in epithelial tumors." (PMID 37274282, 2023). "LIMA1 is also known as epithelial protein lost in neoplasms (EPLIN) and sterol regulatory element binding protein 3 (SREBP3)." (PMID 37274282, 2023). "Here, we describe the identification of LIM domain and actin-binding protein 1 (LIMA1), also known as epithelial protein lost in neoplasm (EPLIN), as a new Az1 target." (PMID 37325974, 2023). "LIMA1 is expected to be a new biomarker for tumor diagnosis, prognostic biomarker and targeted therapy to improve survival of cancer patients in the future." (PMID 37274282, 2023). "This suggests that LIMA1 is expected to be a potential prognostic biological marker and therapeutic target for tumor therapy." (PMID 37274282, 2023). "Overexpression of LIMA1 has been shown to be effective in manipulating tumor characteristics such as reducing cell growth and cell motility and rendering cells less aggressive." (PMID 37274282, 2023). "LIMA1 (LIM domain and actin binding 1), also known as epithelial protein lost in neoplasm (EPLIN), has been known to play differential roles in the progression and metastasis of certain cancers." (PMID 36246561, 2022). "Using TIMER and ssGSEA, we analyzed the connection between LIMA1 and tumor-infiltrating immune cells (TIICs)." (PMID 37181789, 2022). "By evaluating a single-cell database, our study is the first to identify LIMA1 as an essential immune-related prognostic marker in the HNSC tumor microenvironment." (PMID 37181789, 2022). "Lima1 is an extensively studied prognostic marker of malignancy and is also considered to be a tumour suppressor, but its role in a developmental context of non-transformed cells is poorly understood." (PMID 35105859, 2022). "The mechanism through which LIMA1 promotes tumor growth and metastasis in HNSCs warrants additional study." (PMID 37181789, 2022). "Down-regulated MTSS1 and up-regulated LIMA1 were key factors stabilizing the cytoskeleton of tumor cells under μg conditions." (PMID 31261642, 2019). "Notably, LIMA1 not only directly suppresses malignant phenotypes in tumor cells but also modulates immune cell function within the tumor microenvironment." (PMID 41596426, 2026). "We hypothesize that LIMA1 secreted by osteocytes may exert its effects by binding to MYO5B in tumor cells through mechanisms such as membrane fusion or endocytosis." (PMID 41596426, 2026).
tumor (continued). "In summary, our data demonstrate that LRP5-overexpressing osteocyte-derived CM exerts anti-tumor and bone-protective effects in vivo, and that LIMA1 and MYO5B may be relevant factors contributing to these actions within the bone microenvironment." (PMID 41596426, 2026). "Collectively, these findings indicate that LIMA1 functions as a downstream effector of the LRP5/Wnt signaling axis in mediating the anti-tumor actions of LRP5-overexpressing osteocyte-derived CM, and that its knockdown substantially attenuates these inhibitory effects." (PMID 41596426, 2026). "This immunostimulatory pattern was markedly reduced when LIMA1 was knocked down, suggesting that LIMA1 may contribute to the pro-inflammatory, anti-tumor immune microenvironment induced by LRP5-overexpressing osteocyte-derived CM." (PMID 41596426, 2026). "Lower levels of EPLIN-α are linked to advanced disease stages and poorer prognosis, suggesting that LIMA1 may help suppress tumor cell growth and migration." (PMID 40243460, 2025). "In addition, treatment of HCC cells with miR-20a-5p overexpressing CAFs exosomes inhibited LIMA1 expression and promoted lethal tumor progression in vitro and in vivo." (PMID 38463229, 2024). "In recent decades, researchers have identified the epithelial protein lost in neoplasm (EPLIN, also known as LIMA1) as a crucial component in regulating cytoskeletal dynamics (actin and β-catenin) and influencing alterations in cell motility and cell–cell adhesion." (PMID 38732188, 2024). "The role of LIMA1 in malignancy progression has expanded from a tumor suppressor that acts primarily in early disease stages to a metastasis suppressor that may act in late stages to prevent and delay the invasion and spread of primary cancer cells." (PMID 37274282, 2023). "Moreover, LIMA1 inhibits deep tumor infiltration and promotes differentiation, playing an important role in chemotherapy responsiveness." (PMID 37274282, 2023). "DNA demethylation of the LIMA1 promoter region may affect its expression upregulation, positively correlating with tumor metastasis, angiogenesis, and EMT." (PMID 37274282, 2023). "Moreover, LIMA1 particularly plays a crucial role in biological processes such as tumor proliferation, apoptosis, migration, invasion, drug resistance, immune response." (PMID 37274282, 2023). "LIMA1 plays a disruptive role in angiogenesis during cancer development to a certain extent, thus providing a new theoretical basis for the molecular regulation mechanism of the tumor angiogenesis process." (PMID 37274282, 2023). "Therefore, there is an urgent need to further explore the molecular mechanisms by which LIMA1 regulates tumor progression." (PMID 37274282, 2023). "LIMA1 may affect tumor development by regulating tumor-infiltrating cells in the tumor microenvironment (TME)." (PMID 37181789, 2022). "In addition, LIMA1-expressing HNSC tumor tissue was obtained from HPA, and, with this tissue, we were able to: compared to HNSC tumor tissues with low LIMA1 expression, HNSC tumor tissues with high LIMA1 expression stained more intensely." (PMID 37181789, 2022). "Next, we aimed to determine why the tumour growth and chimerism were reduced in Lima1 KO cells." (PMID 35105859, 2022). "In the majority of HNSC tumor tissue samples, LIMA1 expression was detected." (PMID 37181789, 2022). "Our results in pluripotent cells show that Lima1 depletion enables blebbing and suggest that in pathological conditions, this may promote tumour resistance to protease inhibitors." (PMID 35105859, 2022).